TLR4 (toll like receptor 4)
Diseases named in the same sentence as TLR4 in open-access papers (continued):
Sharing a sentence is not in itself a finding about the gene and the disease.
type 2 diabetes (110 papers, 2008 to 2026). "Although the pathogenetic role of TLR4 in diabetic neuropathy remains to be established, polymorphisms of TLR4 have been reported to reduce the prevalence of neuropathy in type 2 diabetes." (PMID 38525707, 2024). "In this study, TLR4 deficiency also prevents or delays the occurrence of type 2 diabetes in mice induced by HSHFD and STZ injection." (PMID 38275739, 2024). "TLR4 activity causes inflammatory effects in Type II diabetes-associated OA, and promotes catabolism in articular cartilage, as demonstrated in an in vitro study on isolates taken from patients undergoing TKR." (PMID 36983885, 2023). "TLR4−/− deletion or inhibition has been shown to improve endothelial dysfunction in mice caused by angiotensin II delivery or type II diabetes." (PMID 39323483, 2023). "In a previous study, a herbal extract named Baihu decoction, which has hypoglycemic and antioxidant effects, significantly inhibited a CD14/TLR4/NF-kB pathway, and its associated inflammation, in a type 2 diabetic mouse model." (PMID 34829669, 2021). "It was also observed that hyperglycemia stimulated the expression of TLR4 in glomerular renal endothelial cells in a mouse model of type 1 and type 2 diabetes, which underlines the relationship of the discussed receptor with diabetic nephropathy." (PMID 32933213, 2020). "For example, genetic polymorphism in the TLR-4 gene is strongly associated with insulin resistance levels in patients with type 2 diabetes." (PMID 29565290, 2018). "Among the various TLRs, TLR-2 and TLR-4 have been most consistently associated with type 1 and type 2 diabetes." (PMID 29565290, 2018). "Glomerular MRP8 expression appears to be associated with progression of proteinuria in obese or type 2 diabetic patients, possibly by inducing inflammatory changes in macrophages through TLR4 signaling." (PMID 24558454, 2014). "An influence of the minor alleles of four TLR4 variants on the incidence of type 2 diabetes was observed particularly for patients with high levels of TC/HDL-C and these findings were supported by haplotype analysis." (PMID 18298826, 2008). "Only few epidemiological studies have investigated the association of TLR4 polymorphisms with type 2 diabetes focusing only on the two classical polymorphisms Asp299Gly and Thr399Ile." (PMID 18298826, 2008). "The authors suggested that TLR4 upregulation may be associated with hyperglycaemia and thus inhibition is theoretically beneficial in treating Type II diabetes mellitus-associated OA." (PMID 36983885, 2023). "Regarding peripheral biomarkers associated to neuropathy, some of those are related to chronic inflammatory state such as the inflammatory cytokine IL-6, and to the innate immune response receptor TLR4 associated more frequently to the severity of neuropathy in type 2 diabetes patients." (PMID 33810048, 2021). "Since several studies have suggested that type 2 diabetes might be associated with changes in the innate immune response, we sought to investigate the association between genetic variants in the TLR4 gene and incident type 2 diabetes." (PMID 18298826, 2008). "Moreover, to our knowledge, there are no published prospective data evaluating the association between TLR4 variants and the development of type 2 diabetes." (PMID 18298826, 2008). "Recently, studies on the relationship between TLR4 gene polymorphism and type 2 diabetes mellitus (T2DM) and its complications have attracted extensive attention." (PMID 35672795, 2022). "In type 2 diabetic patients, there is a low grade systemic inflammation associated with altered T cell populations, including reduced overall T cells, Th17, IL-21R+, Tregs, and TLR4+ T cells, while monocytes show enhanced TLR4 expression; however, the Treg/Th17 ratio was not explored." (PMID 31963845, 2020). "Interestingly, a link between TLR2 and TLR4 polymorphisms and Type 2 diabetes has been documented, suggesting that TLRs may play a causative role in diabetes." (PMID 27478851, 2016).
type 2 diabetes (continued). "The High Mobility Group Box 1 (HMGB1)/TLR4 axis is activated in type 2 diabetic (T2DM) neural tissues, and its inhibition by glycyrrhizin (GLC) improves nociceptive thresholds." (PMID 41574659, 2026). "LPS triggers inflammation by binding to Toll-like receptor 4 (TLR4), a pathway that is upregulated in obese and type 2 diabetes patients." (PMID 39996827, 2025). "Multiple studies employing well-known TLR4 inhibitors have connected TLR4 activation to AD and type 2 diabetes." (PMID 36656815, 2023). "In type II diabetes, the TLR4 function appears dysfunctional with neutrophils exhibiting tolerance behavior when exposed to LPS." (PMID 35677024, 2022). "For instance, it has been shown that the loss or blockage of toll-like receptor 4 (TLR4), attenuates the development of NAFLD and alcohol-related liver diseases and improves insulin signaling in settings of type 2 diabetes." (PMID 36293555, 2022). "It remains an open question whether defects in TLR4 trafficking contribute also to the severity of acute and chronic inflammation caused, respectively, by infection and metabolic endotoxemia, the latter known to participate in the development of type 2 diabetes." (PMID 33057840, 2021). "Recently, the HMGB1/TLR4 expression levels were reported to be up regulated in spinal neurons of type 2 diabetic rodents with painful neuropathy along with marked mechanical and thermal hyperalgesia." (PMID 33915770, 2021). "Our study here provides new evidence that the TLR4-targeted treatment for type 2 diabetes requires caution." (PMID 33376487, 2020). "TLR2 and TLR4 expression and their ligands, signaling, and functional activation are increased in diagnosed type 2 diabetes and contribute to the proinflammatory state." (PMID 32824985, 2020). "In the present study, we demonstrated that hepatic inflammation was increased in HFD/STZ-induced type 2 diabetic mice as evidenced by the upregulation of TLR4, MCP-1, and TNF-α mRNA expression." (PMID 32182914, 2020). "It has already been reported that curcumin, known as a TLR4 inhibitor, can be a candidate for the treatment of metabolic syndrome and type II diabetes mellitus through a clinical trial test." (PMID 33291425, 2020). "Toll-like receptor 4 (TLR4) is a key factor in the innate immune activation of the inflammatory signaling pathway, which plays a critical role in the pathogenesis of type 2 diabetes metabolic inflammation." (PMID 31934590, 2019). "Toll-like receptor 4 (TLR4) is the key marker of meta-inflammation which has an important role in the pathogenesis of metabolic inflammation in type 2 diabetes." (PMID 31950065, 2019). "Previous reports suggested that obese and type 2 diabetes patients have increased the level of TLR4 expression and involvement of NF-κB in human myotubes and p-STAT3 protein activation." (PMID 28706484, 2017). "RAGEs activate indirectly the toll-like receptor 4 (TLR-4), which can trigger interaction with an innate immune system as well in type 2 diabetic patients." (PMID 26881021, 2016). "Increased TLR4 expression leads to type 2 diabetes by reducing insulin secretion by β-cells and together with TLR2 and TLR9 contribute to the development of neurological disorders like schizophrenia and autism." (PMID 27307950, 2016). "Other studies have shown the increased expression of TLR2 and TLR4 in conventional insulin resistance target tissues like skeletal muscle and adipose tissue of Type 2 diabetics." (PMID 27478851, 2016). "Collectively, these studies suggest the contribution of TLR4-mediated signalling to the development of type 2 diabetes." (PMID 24614850, 2014). "This study has demonstrated that in type 2 diabetes a significant immigration of TLR4 positive macrophages occurs into the pancreatic islet." (PMID 24594974, 2014). "For example, the chemokine CXCL10 is highly expressed in islets isolated from individuals with type 2 diabetes and has been shown to impair insulin secretion and promote β-cell apoptosis via TLR4." (PMID 20814545, 2010).
type 2 diabetes (continued). "In men, the effect of TLR4 haplotypes H5 and H7 on incident type 2 diabetes was modified by TC/HDL-C." (PMID 18298826, 2008). "The effect of TLR4 SNPs on incident type 2 diabetes was modified by the ratio of total cholesterol to high-density lipoprotein cholesterol (TC/HDL-C)." (PMID 18298826, 2008). "In men the effects of TLR4 SNPs and haplotypes on incident type 2 diabetes were modified by TC/HDL-C concentrations." (PMID 18298826, 2008). "Our In Silico data also indicated that Apigetrin and Rutin might block human TLR4, which could be useful in type 2 diabetes protein Tetrameric 11B-HSD1I and human pancreatic alpha-amylase those our result are similar with previous literature." (PMID 38887700, 2024). "However, it was reported that mRNA expression of TLR4 is elevated in obese and type 2 diabetes patients, and TLR4 protein is higher in males compared with females in peripheral blood mononuclear cells." (PMID 37028769, 2023). "TLR4 has been reported to be involved in the synthesis and release of visfatin, and visfatin plasma concentrations increased in patients with obesity, type II diabetes mellitus, and MetS." (PMID 36983885, 2023). "In addition, in patients with type II diabetes and confirmed diabetic kidney disease, microalbuminuria, mRNA, and TLR4 protein were overexpressed 4 to 10 times more in glomeruli and tubules compared to the control group." (PMID 32933213, 2020). "However, both TLR2 and TLR4 expression was increased on monocytes in patients with type II diabetes." (PMID 32933213, 2020). "Our results indicate that the TRIF-dependent TLR signaling contributes to maintaining insulin/AKT signaling and M2 macrophages in epididymal adipose tissue under a normal chow diet and provide new evidence that TLR4-targeted therapies for type 2 diabetes require caution." (PMID 33376487, 2020). "We also observed the in vitro effect of HG on the upregulated expression of TLR-2 and TLR-4 on the cell surface of primary monocytes from healthy subjects, similar to recently diagnosed type 2 diabetic patients, supporting the upregulation of TLRs in the presence of HG concentrations." (PMID 31815150, 2019). "It was reported in a German population that Asp299Gly and Thr399Ile genotypes of the TLR4 were associated with diabetic neuropathy in type 2 diabetes, but not with diabetic nephropathy." (PMID 24779014, 2014). "It was recently revealed that FFA are mediators of toll-like receptor (TLR)-4 and the NF-kappaB pathway of macrophages within adipose tissue and are regarded as key molecules in systemic inflammation, which plays a role in type 2 diabetes and cardiovascular disease." (PMID 22496600, 2012). "Previous studies demonstrate that both mRNA expression and protein content of the membrane-bound receptor of LPS, Toll-like receptor 4 (TLR4), as well as NF-κB activity are elevated in unstimulated conditions in skeletal muscle of patients with type 2 diabetes." (PMID 21931634, 2011). "Moreover, skeletal muscle TLR4 gene and protein expression are significantly elevated in muscle from obese subjects with type 2 diabetes." (PMID 20814545, 2010). "The effect of TLR4 SNPs on incident type 2 diabetes was modified by TC/HDL-C in men." (PMID 18298826, 2008). "Evidence for a role of TLR4 in type 2 diabetes came from in-vitro studies." (PMID 18298826, 2008). "None of the SNPs in the TLR4 gene was significantly associated with incident type 2 diabetes in multivariate-adjusted models including age, BMI, SBP, TC/HDL-C, survey, smoking status, alcohol consumption and physical activity." (PMID 18298826, 2008). "Similarly, TLR4 overexpression has also been observed in type 2 diabetes patients." (PMID 38275739, 2024).
type 2 diabetes (continued). "In addition, low doses of LPS derived from the gut microbiota can in certain conditions enter the bloodstream and evoke so-called metabolic endotoxemia leading to a chronic low-grade TLR4-dependent inflammation which contributes to the development of metabolic diseases, such as type 2 diabetes." (PMID 33057840, 2021). "Moreover, it can be suggested that TLR2 and TLR4 may be a promising therapeutic targets to prevent or retard the DNP in type 2 diabetic patients." (PMID 33442388, 2020). "Therefore, TLR2 and TLR4 may be a promising therapeutic target to prevent or retard DNP in type 2 diabetic patients." (PMID 33442388, 2020). "We conclude that minor alleles of several TLR4 variants, although not directly associated with type 2 diabetes might increase the risk for type 2 diabetes in subjects with high TC/HDL-C." (PMID 18298826, 2008). "Increased TLR4 expression in DKD upregulates inflammatory response and releases the fibrosis-related factors in type 2 diabetes (T2DM) and its chronic complications." (PMID 39133777, 2024). "Previous studies have detected higher expression of TLR4 and TNF-α in obese as compared to lean subjects with a remarkably higher expression in obese and overweight individuals with type 2 diabetes." (PMID 37964189, 2023). "We recently reported that TLR2 and TLR4 localize on the glomerular endothelium in the glomeruli of STZ-induced type 1 diabetic mice and in high fat diet feed-induced type 2 diabetic mice." (PMID 29018490, 2017). "TLR4 protein content and ERK signaling were elevated in the type 2 diabetes group, which were slightly but significantly older than the lean and obese groups." (PMID 23671849, 2013). "Given that insulin-resistant subjects (either with obesity or type 2 diabetes) have elevated plasma FFA concentrations due to excessive lipolysis, TLR4 and downstream pathways in monocytes could be a mechanistic link between FFA and inflammation." (PMID 29649324, 2018). "In another study, with type 2 diabetic patients, in which TLR expression in mononuclear cells was monitored in response to low-dose insulin infusion, a further relationship between TLR2 and TLR4, and insulin homeostasis was identified." (PMID 21356084, 2011). "In the present study, the effect of TLR4 SNPs on incident type 2 diabetes was modified by TC/HDL-C in men, but not in women." (PMID 18298826, 2008). "Thus, TLR4 could represent an attractive therapeutic target not only for the early treatment of MASLD, but also for preventing type 2 diabetes development by targeting islet macrophages." (PMID 40387904, 2025). "However, in patients with type 2 diabetes and confirmed biopsy, diabetic kidney disease has been found to increase TLR4 expression on renal tubules as opposed to TLR2." (PMID 32933213, 2020). "Our results showed that the subjects with type-2 diabetes had significantly elevated mRNA levels of TLR2 and TLR4 as compared with non-diabetic obese subjects." (PMID 23191980, 2012).
metabolic syndrome (103 papers, 2009 to 2026). A cluster of metabolic risk factors for CARDIOVASCULAR DISEASES and TYPE 2 DIABETES MELLITUS. "Specific genetic variations: Genetic variations in genes such as TGFB1, IL6, and TLR4 are associated with a higher probability of adverse effects and metabolic syndrome." (PMID 39246917, 2024). "As such, the combination of altered lipid metabolism as seen through increased LDL combined with LPS/TLR-4 mediated oxidization, worsens dyslipidemia leading to more severe associated clinical sequelae." (PMID 36615885, 2023). "TLR4 activation has been implicated in the development of dyslipidemia and associated atherosclerosis, through enhanced release of pro-inflammatory cytokines like IL-8, IL-1beta and TNF-alpha." (PMID 36615885, 2023). "We investigated IL-1, IL-6 and TNFα production and toll-like receptor 4 in both—obese and lean patients with non-alcoholic fatty liver disease who met different sets of metabolic syndrome criteria and linked the results with the disease burden." (PMID 26629827, 2015). "The purpose of this study was to investigate the effects of dyslipidemia on osteoclast differentiation associated with TLR2 and TLR4 in periodontal tissues using a rat dyslipidemia (apolipoprotein E deficient) model." (PMID 23295061, 2013). "A recent publication reports that TLR4 mRNA is increased in patients with metabolic syndrome, which also is a risk factor for cardiometabolic diseases." (PMID 24194869, 2013). "Further studies should investigate the role of TLR4 Asp299Gly and additional polymorphisms of TLR4 to understand the potential effects of innate immunity on lung function in relation to metabolic syndrome." (PMID 19772581, 2009). "It is essential to understand and investigate the interplay between lung function, TLR4 Asp299Gly polymorphism and metabolic syndrome in humans." (PMID 19772581, 2009). "It is hypothesized that increasing serum fatty acids associated with metabolic syndrome stimulate TLR4 leading to increased serum levels of TNF-alpha, IL-1B, and IL-6." (PMID 33072103, 2020). "Mounting evidence indicates that air pollutions are associated with a high incidence of NAFLD and metabolic syndrome through the activation of Kupffer cells, c-Jun N-terminal Kinases-activator protein 1, nuclear factor-κB, Toll-like receptor-4, and peroxisome proliferator-activated receptors." (PMID 31801197, 2019). "As TLR4 is known to contributed to hyperlipidemia, we wondered whether the more severe dyslipidemia phenotype in TLR2-deficient offspring-pLPS was due to TLR4 activity." (PMID 31507457, 2019). "Also consistent with our findings, TLR4 expression in peripheral mononuclear cells was reduced in overweight individuals with metabolic syndrome undergoing weight loss." (PMID 29649324, 2018). "Interestingly, TLR4 expression in peripheral blood mononuclear cells is reduced in overweight individuals with metabolic syndrome that undergo weight loss." (PMID 20814545, 2010). "Additionally, pattern recognition receptors like TLR4 are essential for intestinal innate immunity and inflammatory activation, and their activation is associated with inflammatory responses induced by dyslipidemia." (PMID 40342858, 2025). "Genetic polymorphism in the TLR4 gene could influence metabolic syndrome (MS) susceptibility." (PMID 39459627, 2024). "Single nucleotide polymorphisms (SNPs): SNPs in genes like IL1B, IL10, TLR4, and CASP5 are linked to specific adverse effects such as gastrointestinal toxicity, which contributes to metabolic syndrome." (PMID 39246917, 2024). "Metabolic syndrome associated inflammatory markers such as, IL-1β, MCP-1, TLR-4 and TNF-α were quantified in dietary lipid supplemented healthy and diabetic groups." (PMID 38755663, 2024). "LPS also seems to promote IR, dyslipidemia, hepatic inflammation, and fibrosis through activation of Toll-like receptor 4 (TLR4) and LPS binding protein in the gut, liver, and adipose tissue." (PMID 38445874, 2024).